ADD1 (adducin 1)
Diseases named in the same sentence as ADD1 in open-access papers (continued):
Sharing a sentence is not in itself a finding about the gene and the disease.
coronary heart disease (3 papers, 2013 to 2020). "Among the three adducin genes, ADD1 has received more attention than the other two due to its association with several diseases, such as hyperlipidemia, renal disease, and coronary heart disease." (PMID 23509723, 2013). "Additionally, the polymorphism (p.G460W) present in ADD1 has reportedly contributed to the increased risk factor for coronary heart disease." (PMID 32760426, 2020).
Obesity (3 papers, 2015 to 2023). Accumulation of substantial excess body fat. "Third, data on certain other risk factors including family history, obesity and ulcerative colitis were not fully collected during the investigation, with the result that the ORs of CRC risk could not be adequately adjusted to estimate the risk effect of ADD1-rs4963." (PMID 25816007, 2015).
atherosclerosis (2 papers, 2020 to 2021). A disease characterized by the build-up of fatty material and calcium deposition in the arterial wall resulting in partial or complete occlusion of the arterial lumen. "Our study identified seven core genes (UQCR11, UBE2N, ADD1, TLN1, IRAK3, LY96, and MAP3K1) that are strongly linked to FH and lead to a higher risk of atherosclerosis." (PMID 32760426, 2020). "Through analysis of the public database, seven hub genes (UQCR11, UBE2N, ADD1, TLN1, IRAK3, LY96, and MAP3K1) have recently been found to be strongly associated with familial hypercholesterolemia and contribute to a higher risk of atherosclerosis." (PMID 34895070, 2021).
gastric cancer (2 papers, 2015 to 2017). A primary or metastatic malignant neoplasm involving the stomach. "Recently, a missense variant at the codon of ADD1’s phosphorylation site, rs4963 (Ser586Cys), was reported to modify the risk of non-cardia gastric cancer." (PMID 25816007, 2015).
non-small cell lung carcinoma (2 papers, 2018 to 2022). A group of at least three distinct histological types of lung cancer, including non-small cell squamous cell carcinoma, adenocarcinoma, and large cell carcinoma. "The downregulation of ADD1 promoted the migration of non-small cell lung cancer cells, and the overexpression of ADD1 exerted the opposite effect." (PMID 35513851, 2022). "Without having any effects on cell proliferation, stable knockdown of either ADD1 and ADD3 increased migration of non-small-cell lung cancer cells (NSCLC), and overexpression of ADD1 reduced its migration and invasion activities." (PMID 29862265, 2018).
basal cell carcinoma (1 paper, 2023). A carcinoma involving the basal cells. "In basal cell carcinoma and squamous cell carcinoma, ADD1 is increased, implying that ADD1 participates in cell proliferation." (PMID 38253025, 2023).
breast carcinoma (1 paper, 2019). "Depletion of Cdk5 by short-hairpin RNA (shRNA) in breast cancer cells MDA-MB-231 significantly diminished ADD1 T724 phosphorylation." (PMID 31548578, 2019). "The increased lamellipodia formation and cell migration of human breast cancer cells MDA-MB-231 by EGF were accompanied by Cdk5 activation and increased phosphorylation of ADD1 at T724." (PMID 31548578, 2019). "We found that the expression levels of p35 and ADD1 were higher in metastatic breast cancer cells MDA-MB-231 than in non-metastatic breast cancer cells MCF7." (PMID 31548578, 2019). "In this study, we identified ADD1 as a novel substrate of Cdk5 and demonstrated that ADD1 phosphorylation at T724 by Cdk5 is important for EGF-induced cell migration and invasion in MDA-MB-231 breast cancer cells." (PMID 31548578, 2019).
breast invasive carcinoma (1 paper, 2022). "The CNA of ADD1 is correlated with nearly all cancer types, although it is most strongly correlated with breast invasive carcinoma." (PMID 35513851, 2022). "The stage of breast invasive carcinoma was correlated with AGTR1 and ADD1." (PMID 35513851, 2022). "However, the relevance of these genes, including ADD1, in breast invasive carcinoma has not been reported." (PMID 35513851, 2022).
fatty liver (1 paper, 2019). "MD001 alleviated fatty liver by reducing TG and FFA levels in db/db mice, which was associated with increased expression levels of ACOX, CPT, and MLYCD and decreased expression levels of ADD1, ACC, and FAS by PPARα activation." (PMID 30733541, 2019).
gastroschisis (1 paper, 2024). Gastroschisis is marked by viscera protruding, without a covering sac, from the fetal abdomen on the right lateral base of the umbilicus. "Padula investigated 75 genetic variants in 20 genes and found 11 gastroschisis-associated variants in NOS3, ADD1, GNB3, ICAM1, ICAM4, ICAM5, and NAT1 genes." (PMID 39728087, 2024). "Besides ICAM1, the study from the Torfs group also identified a heterozygous/homozygous variant of NOS3, NPPA, ADD1, SERPINE1, and SELE, genes involved with cell–cell interactions, inflammation, or blood pressure, associated with gastroschisis." (PMID 39728087, 2024).
generalized lipodystrophy (1 paper, 2025). Almost complete absence of subcutaneous and/or visceral adipose tissue. "We are testing the V7-LEP gene therapy in a congenital generalized lipodystrophy model, aP2-SREBP1c transgenic mice that overexpress human nuclear sterol regulatory element-binding protein-1c (nSREBP-1c/ADD1) specifically in adipose tissue." (PMID 40709262, 2025).
HCMV infection (1 paper, 2018). "Accordingly, we hypothesized that ADD1 and SULF1 methylation were related to HCMV infection and induction of EH in the Kazakh population." (PMID 29752343, 2018).
hemorrhagic stroke (1 paper, 2022). A stroke caused by a bleed on the brain. "A sequencing study suggested that ADD1 polymorphism significantly increased the susceptibility to ischemic and hemorrhagic strokes." (PMID 35465608, 2022).
Infertility (1 paper, 2022). "The deletion of C11orf94 leads to infertility in mice by affecting the expression of calcium pathway related proteins such as PDE1C, LGMN and ADD1, as well as sperm-oocyte fusion related proteins such as CRISP1, IZUMO1 and EQTN in mouse sperm." (PMID 36050562, 2022).
ischemic stroke (1 paper, 2013). A stroke disorder caused by obstruction of blood flow to the brain, due to thrombotic (local blood clot formation) or embolic (due to a blood clot or other material traveling from another site) event. "Of these IL-1α, CYP11B2, ESR1 (PVUII), α ADD1, TNF α (G488A), CYP4F2, MDR-1 and t-PA (I/D) were found to be significantly associated with ischemic stroke." (PMID 23505425, 2013).
lung adenocarcinoma (1 paper, 2022). A carcinoma that arises from the lung and is characterized by the presence of malignant glandular epithelial cells. "ADD1 expression was downregulated in lung adenocarcinoma tissues compared with that in normal lung tissues." (PMID 35513851, 2022).
melanoma (1 paper, 2024). A malignant, usually aggressive tumor composed of atypical, neoplastic melanocytes. "In conclusion, this study provides insight into the potential mechanisms underlying Si162 resistance in melanoma cells and identified 5 genes (CNTN6, ADD1, FGF18, C18orf25, and RPL13) as potential prognostic biomarkers for Si162 resistance." (PMID 38665777, 2024).
ovarian carcinoma (1 paper, 2017). A malignant neoplasm originating from the surface ovarian epithelium. "By transcriptional profiling and stringent data mining criteria, one research identified that ADD1 expression were up-regulated by estradiol-17β (E2) in human ovarian surface epithelial but down-regulated by estrogen in ovarian cancer (OVCA) cells." (PMID 28476036, 2017). "It was also found that ADD1 overexpression in OVCA cells was associated with reduced cell proliferation, soft agar, colony formation and invasion, suggesting adducin functions as a tumor suppressor in ovarian cancer cells." (PMID 28476036, 2017).
small cell lung carcinoma (1 paper, 2017). Small cell lung cancer (SCLC) is a highly aggressive malignant neoplasm, accounting for 10-15% of lung cancer cases, characterized byrapid growth, and early metastasis. "One study found that HGF and c-MET were overexpressed in small cell lung cancer (SCLC) and ADD1 was one of the downstream of HGF/c-MET signaling pathway." (PMID 28476036, 2017).
virus infection (1 paper, 2025). "Consequently, PKC/ADD1/F‐actin is an attractive target for the development of antiviral drugs to prevent multiple virus infections utilizing intracellular vesicular transport system." (PMID 40472230, 2025). "The early successive steps of virus infection were further probed, and ADD1 did not function in either IAV attachment or internalization processes." (PMID 40472230, 2025).
cancer (4 papers, 2015 to 2025). A tumor composed of atypical neoplastic, often pleomorphic cells that invade other tissues. "This work not only unveils the mechanism of Cdk5 in regulating cell migration and invasion through ADD1, but also highlights the role of ADD1 in cancer progression." (PMID 31548578, 2019). "Indeed, elevated activation of Cdk5 and PKCδ and increased phosphorylation of ADD1 at T724 and S726 were detected in the highly metastatic cancer cells." (PMID 31548578, 2019). "Binding that was induced in cancer, but not in the normal tissues, was displayed by the transcription factors E2F1, AP3, LIII-BP, PAX6, ADD-1, and CCAC." (PMID 25861239, 2015).
tumor (4 papers, 2018 to 2023). "Finally, the risk score was calculated by the following formula: tumor-associated endothelial signature score = 0.180855332*ADD1 + 0.059530341*ALOX12 + 0.145361104 *CXCL10 - 0.081730252*F2RL1 + 0.001225741*ITGAX − 0.004914148*MET." (PMID 37719845, 2023).
infection (2 papers, 2019 to 2025). The state of being infected such as from the introduction of a foreign agent such as serum, vaccine, antigenic substance or organism. "The results showed that endocytic viruses like VSV and PEDV induced an upregulation of ADD1 phosphorylation at Ser726 during early infection." (PMID 40472230, 2025). "Using a conditional knockout model, we show that Add1 is necessary for complete activation of CD4+ T cells in response to low levels of antigen but is dispensable for CD8+ T cell activation and response to infection." (PMID 31824498, 2019).
ADD1 also shares sentences with these, for which no sentence is quoted: essential hypertension (10 papers); Hyperglycemia (2); hyperlipidemia (2); neurodevelopmental disorder (2); renal disease (2); animal diseases (1); central obesity (1); cerebral palsy (1); cervical cancer (1); depression (1); diabetes (1); diabetic retinopathy (1); familial hypercholesterolemia (1); head and neck squamous cell carcinoma (1); hypertriglyceridemia (1); influenza (1); left ventricular hypertrophy (1); lung squamous cell carcinoma (1); lymphopenia (1); metastatic colorectal cancer (1); myocardial infarction (1); peripheral arterial disease (1); squamous cell carcinoma (1); ulcerative colitis (1).